SFRP1 (secreted frizzled related protein 1)
Diseases named in the same sentence as SFRP1 in open-access papers (continued):
Sharing a sentence is not in itself a finding about the gene and the disease.
breast carcinoma (continued). "Our analysis of stromal changes between non-metastatic and metastatic canine mammary carcinomas highlighted molecular differences in the tumour microenvironment, including changes in VIT, TGFBR2, TGFBR3, LTBP4 and SFRP1." (PMID 37391533, 2023). "In a breast cancer context, the accumulation of Wnt molecules due to the TGF-β pathway, combined with the lack of SFRP1, result in a dramatic over-activation of the Wnt signaling pathway and, consequently, in an increasing cell proliferation." (PMID 31947616, 2020). "The breast cancer cell lines BT20 and SKBR3 were chosen for these in vitro models because they do not exhibit any endogenous SFRP1 expression and they belong to different molecular subgroups of human breast cancer cell lines." (PMID 25036590, 2014). "Next, we wanted to decipher whether the positive correlation between SFRP1 and BDNF expression on the one hand and the negative correlation between SFRP1 and LY96 expression on the other hand is also detectable in human breast cancer." (PMID 25036590, 2014). "When SFRP1 is knocked down in immortalized non-malignant mammary epithelial cells, the cells (TERT-siSFRP1) acquire a malignant phenotype characteristically observed in metastatic breast cancer stem-like cells." (PMID 22928951, 2012). "When SFRP1 is knocked down in immortalized non-malignant mammary epithelial cells, the cells (TERT-siSFRP1) exhibit a malignant phenotype which resembles the characteristics observed in metastatic breast cancer cells." (PMID 21303533, 2011). "SFRP1 was correlated to pathological complete response and relapse-free survival status at 5 years in breast cancer regardless of any chemotherapy, hormone therapy, and anti-HER2 therapy, therefore, SFRP1 could act as a predictive biomarker to predict response among patients with breast cancer." (PMID 37963835, 2023). "As a reminder, the decrease in SFRP1 expression in non-tumoral (MCF10A) and pre-tumoral (MCF10AT1) breast lesions was inversely correlated with ESR1 expression, highlighting the existence of a differential role of SFRP1 with regards to breast cancer stage and molecular subtype." (PMID 37190179, 2023).
gastric cancer (34 papers, 2007 to 2025). A primary or metastatic malignant neoplasm involving the stomach. "On the other hand, in gastric cancer, overexpressed SFRP1 gene was associated with the activation of transforming growth factor-beta (TGFβ) signaling pathway that induced cell proliferation, epithelial–mesenchymal transition (EMT) and invasion." (PMID 33007803, 2020). "In gastric cancer, SFRP1 methylation was associated with loss of SFRP1 expression and occurred in the early event of this cancer." (PMID 32074995, 2020). "Although in many cancers sFRP1 is inactivated due to epigenetic modification, but it is also known to be over-expressed in gastric cancer and renal cell carcinoma where it is associated with tumor aggressiveness, metastasis, and decreased overall survival." (PMID 30513115, 2018). "It should be noted, though, that down regulation of sFRP-1 predisposes the mammary gland to tumorigenesis while sFRP-2 is significantly downregulated in gastric cancer, and downregulation of both sFRP-1 and sFRP-2 contributes to cervical cancer progression." (PMID 20948575, 2010). "The methylation of the promoter region of the secreted frizzled-related protein 1 (SFRP1) holds potential as a diagnostic indicator and therapeutic target, particularly in specific malignancies like ampullary adenocarcinoma and gastric cancer, where its upregulation is linked to poor prognoses." (PMID 39236081, 2024). "Secretory frizzled-related protein 1 (sFRP1) has elevated expression in gastric cancer tissues, with its up-regulation facilitated by the Wnt/β-catenin signaling pathway." (PMID 41188920, 2025). "Overexpression of SFRP1 in gastric cancer cells enhance cell growth and migration through Rac and GSK3β dependent mechanisms." (PMID 37091166, 2023). "The HDAC inhibitor, sodium butyrate, restored histone modifications in the promoter regions of SFRP1, two genes found in gastric cancer cells." (PMID 35892344, 2022). "The down-regulation of SFRP1 has been observed in a variety of solid tumors such as gastric cancer, colorectal cancer, etc., suggesting that the inactivation of SFRP1 is an essential prerequisite for cell differentiation and carcinogenesis." (PMID 35892344, 2022). "In contrast, knockdown of miR-27a in gastric cancer cell line resulted in increased SFRP1 mRNA and at the same time decreased the expression of Wnt and β-catenin." (PMID 32074995, 2020). "Previous studies have shown that miR-27a modulates gastric cancer cell metastasis by promoting the epithelial–mesenchymal transition (EMT) pathway in gastric cancer and targets SFRP1 to regulate the proliferation and the migration of osteosarcoma cells." (PMID 33282723, 2020). "SFRP1 exhibited a tumor-promoting function by selectively activating TGFβ signaling in gastric cancer cells and thus activating EMT progression." (PMID 33193589, 2020). "SFRP1 overexpression of is detected in human gastric cancer and correlated with lymph node metastasis and poor patient prognosis." (PMID 32764696, 2020). "MiR-208a is capable of promoting gastric cancer progression by suppressing SFRP1 and downregulating MEG3." (PMID 30911286, 2019). "It has been reported that sFRP1 over-expression in gastric cancer cells correlates with the activation of TGF β-catenin pathway, which is in-turn responsible for the invasiveness of cancer." (PMID 30513115, 2018). "In contrast, in gastric cancer cells Shin and colleagues demonstrated that butyrate induced SFRP1-promoter demethylation and restored expression levels." (PMID 28077379, 2017). "We explored the role of secreted frizzled-related protein 1 (sFRP1) overexpression in gastric cancer and its relationship with radiological findings from dual-energy spectral CT(DEsCT) and positron emission tomography/computed tomography (PET/CT)." (PMID 28169332, 2017). "The expression and methylation status of four SFRP members (SFRP1, 2, 4, and 5) in primary gastric cancer samples was screened." (PMID 17848950, 2007).
gastric cancer (continued). "Also, we found that CAF2 up-regulated Wnt signaling pathway genes such WNT2 and WNT5A while down-regulating the expression of Wnt signaling inhibitor SFRP1, which was consistent with findings from the research on CAFs for gastric cancer." (PMID 39256364, 2024). "Similarly, SFRP1 was also found to be over-expressed in metastatic renal cell carcinomas but not in primary tumors, and this was further verified in gastric cancer cells." (PMID 32074995, 2020). "For example, during the development of prostate cancer, sFRP1 secreted from tumor stroma can provide a pro-proliferative signal to adjacent prostate epithelial cells; in gastric cancer, crosstalk of sFRP1 with TGFβ signaling promotes cell proliferation, EMT and invasion." (PMID 32293507, 2020). "Furthermore, high levels of sFRP1 indicate aggressiveness in some subgroups of gastric cancer and poor survival of patients." (PMID 32293507, 2020). "miR-27a was highly expressed in gastric cancer tissues and cells, and it might promote cell proliferation, migration and invasion by targeting SFRP1 via the activation of Wnt/β-catenin signaling pathway." (PMID 32742189, 2020). "This preliminary study demonstrates that sFRP1 overexpression in gastric cancer cells leads to increased cell proliferation and angiogenesis, which may, in turn, contribute to positive PET/CT and CT performances." (PMID 28169332, 2017). "Additionally, we demonstrated that sFRP1 overexpression in gastric cancer induces positive performance in imaging modalities." (PMID 28169332, 2017). "In conclusion, sFRP1 overexpression in gastric cancer cells leads to more angiogenesis and increasing proliferation, which may, in turn, induce positive PET/CT and CT performance." (PMID 28169332, 2017). "MiR-196a could promote the invasion and metastasis of gastric cancer by targeting SFRP1; miR-383-5p was downregulated and might act as a tumor suppressor for gastric cancer, and miR-374a has been reported to act as a biomarker for the diagnosis and prognosis of gastric cancer." (PMID 32192507, 2020). "This study also demonstrated that the over-expression of SFRP1 activates TGF-β activity, which is correlated with cell proliferation, epithelial–mesenchymal transition (EMT), and invasion in gastric cancer cells." (PMID 32074995, 2020). "Paradoxically, miR-940 has been demonstrated to promote tumor cell invasion and metastasis by downregulating GSK3β/sFRP1 and ZNF24 in gastric cancer, respectively." (PMID 28423620, 2017). "What’s more, our team has been worked on some of the differential genes such as PHF10, CEACAM6, SFRP1, SOX11, CLDN1 to investigate their expression and functions in gastric cancer and the results perfect proved our microarray data." (PMID 25928635, 2015). "We previously showed that SFRP1, SFRP2 and SFRP5 are frequently inactivated in CRC and gastric cancer (GC), and that SFRPs suppress constitutive Wnt signalling when overexpressed in CRC and GC cells." (PMID 18283316, 2008). "Additionally, in gastric cancer, high expression of ankyrin repeat and SOCS box-containing 5 (ASB5), secreted frizzled-related protein 1 (SFRP1), SMYD1, and tachykinin receptor 2 (TACR2) is associated with short survival times and high risk in these patients." (PMID 39482529, 2024). "It was recently reported that levels of SFRP1 and SFRP2 transcription correlate inversely with the methylation levels in samples of gastric mucosa, with or without H. pylori infection, as well as background mucosa in gastric cancers." (PMID 32092099, 2020). "However, the role Wnt-antagonist genes including SFRP1, SFRP2, SFRP4, and SFRP5 in gastric cancer remains poorly defined." (PMID 17848950, 2007). "sFRP1 reinstates glycogen synthase kinase 3β (GSK3β) activity, thereby facilitating Rac1 activation, while ectopic overexpression of Rac1 concurrently suppresses SMAD family member 3 (Smad3) activity; these interactions collectively enhance the malignant phenotype of EMT in gastric cancer." (PMID 41188920, 2025).
gastric cancer (continued). "Fourth, and most importantly, only SFRP2, but not SFRP1 silencing by promoter methylation was observed in oral SSC and gastric cancer, and promoter methylation is significantly higher in SFRP2 than SFRP1 in cervical cancer, as well as in cervical adenocarcinoma." (PMID 22384081, 2012).
colorectal cancer (32 papers, 2006 to 2026). A primary or metastatic malignant neoplasm that affects the colon or rectum. "Downregulation of Sfrp1 has been reported in colorectal cancer, and low expression levels of Sfrp1 have been associated with poor prognosis in colorectal cancer patients." (PMID 38748896, 2024). "Our previous studies identified loss of sFRP1 expression at the premalignant stage of colorectal cancer development." (PMID 20628379, 2010). "Our previous studies have implicated the Wnt antagonist, sFRP1, as a tumour suppressor gene in advanced colorectal cancer." (PMID 16523202, 2006). "It is unlikely, therefore, that catenin-mediated transcription is responsible for the downregulation of sFRP1 expression seen in colorectal cancer, indicating that this is caused by an independent event in early colorectal tumorigenesis." (PMID 16523202, 2006). "In our study, TCGA analysis revealed that genes such as those from the SPRR family, MUC6, KRT family, SLC26A9, MMP7, PRSS56, and SFRP1 were highly expressed in the colorectal cancer group." (PMID 41595533, 2026). "A heatmap of the top 50 differentially expressed genes was generated, highlighting that genes such as SPRR family members, MUC6, KRT family genes, SLC26A9, MMP7, PRSS56, and SFRP1 were highly expressed in the colorectal cancer group." (PMID 41595533, 2026). "This study aimed to investigate the expression, prognostic significance, methylation, and immune invasion levels of secreted frizzled-related proteins (SFRP1-5) in colorectal cancer (CRC)." (PMID 39729237, 2025). "Based on these, we inferred that by inhibiting miR-31, a-actin expression, and MMP expression, MEG3 can promote the expression of SFRP1, which in turn inhibits the migration and invasion ability of colorectal cancer cells." (PMID 38309281, 2023). "Since previous studies have confirmed SFRP1 to be an important regulator of cancer cell motility in skin tumor and colorectal cancer cell lines, few studies have reported the cell characteristics in OSCC." (PMID 35892344, 2022). "Downregulation of sFRP1 by hypermethylation has been shown to be essential for self-renewal of colorectal cancer stem cells." (PMID 34552611, 2021). "In human colorectal cancer cells, miR-27a promotes cell proliferation and migration by regulating Sfrp1 to activate the Wnt/β-catenin signalling pathway." (PMID 32484208, 2020). "In accordance, it was shown that the SFRP1-mediated inhibition of the WNT pathway was independent from wildtype or mutant β-catenin in colorectal cancer cells." (PMID 32189106, 2020). "This corresponds to the pattern we observed previously for sFRP1 in established colorectal cancers, indicating that expression is suppressed by another, dominant, mechanism." (PMID 16523202, 2006). "We previously showed that the secreted Wnt antagonist sFRP1 is downregulated in most established colorectal cancers and that this coincides with increased methylation of the gene." (PMID 16523202, 2006). "In this study, we set out to investigate the relationship between sFRP1 expression and large bowel adenomas, a precursor of colorectal cancer." (PMID 16523202, 2006). "Interestingly, Sfrp1 has been demonstrated to regulate cell proliferation in multiple tumours such as myeloid leukaemia, ovarian cancer and colorectal cancer." (PMID 38748896, 2024). "Recent studies have showed down-regulation of SFRP1 expression in colorectal cancer (CRC)." (PMID 29610564, 2018). "Previous studies have reported that SFRP1 promoter hypermethylation could serve as an epigenetic biomarker for cancer detection, progression and prognosis for breast and colorectal carcinomas." (PMID 27385214, 2016). "Hypermethylation of the selected markers (MAL, PRIMA1, PTGDR and SFRP1) can result in reduced gene expression and may contribute to the formation of colorectal cancer." (PMID 26482433, 2015).
colorectal cancer (continued). "However, in parallel it was found that the other members of the SFRP family (SFRP1, -2, -4 and -5) were methylated in different types of cancer, such as breast and colorectal cancer." (PMID 21494614, 2011). "Lithium treatment of a small bowel mucosal cell line (FHs 74 int) induced sFRP1 within 8 h, indicating that this gene is positively regulated by β-catenin, contrasting with the suppression of sFRP1 expression, we saw previously in advanced colorectal cancers." (PMID 16523202, 2006). "This study identifies sFRP1 inactivation at the premalignant stage of colorectal cancer development, indicating that these pathways may be useful targets for chemoprevention strategies in this common solid tumour." (PMID 16523202, 2006). "Our previous studies demonstrated that deletion of the sFRP1 gene in early colorectal tumours is a rare event, and we therefore postulated that methylation of the promotor region suppresses expression, as we have previously identified to be the case in advanced colorectal cancer." (PMID 16523202, 2006). "FABP6, hypermethylated SFRP1, XDH, PLAU, ADH1C, HSD17B2, and SPP1 have been identified more as a colorectal cancer biomarker than as a therapeutic target at present." (PMID 34381520, 2021). "SFRP1, SFRP2, and DKK2 were appropriate markers to differentiate colorectal cancer cells from normal crypt cells." (PMID 28533824, 2017). "To better elucidate the role of SFRP1 in CRLM, we employed several preclinical models, including subcutaneous tumor, patient derived organoids (PDOs), patient derived xenografts (PDXs), and orthotopic colorectal cancer metastasis models." (PMID 40225580, 2025). "Interestingly, we found that four of the markers best suited to distinguish cases from controls in our study were the already well-known colorectal cancer markers IKZF1, SFRP1, SFRP2 and VIM." (PMID 37438612, 2023). "Moreover, In vitro studies showed that overexpression of SFRP1, SFRP2 and SFRP5 in colorectal cancer cells resulted in decreased levels of overall cytoplasmic and nuclear β-catenin and decreased colony formation, suggesting a tumor-suppressing effect of SFRP1." (PMID 29610564, 2018). "In addition, our results suggest that SFRP1, SFRP2, and DKK2 markers can differentiate colorectal cancer cells from normal crypt cells." (PMID 28533824, 2017). "Finally, in the simulated colorectal tumor data for the eight patients, we demonstrated the robustness of REOs against PTEC variations by analyzing two genes, SFRP1 remarkably under-expressed in colorectal tumor tissues and ACTA2 over-expressed in malignant colorectal tumor stromal cells." (PMID 28427173, 2017).